KRAS (KRas proto-oncogene, GTPase)
Diseases named in the same sentence as KRAS in open-access papers (continued):
Sharing a sentence is not in itself a finding about the gene and the disease.
tumor (continued). "Notably, transcriptional downregulation of KRAS has been demonstrated to be lethal to tumor cells with aberrant KRAS signaling, irrespective of mutational status, and to have a wide potential therapeutic window." (PMID 36011352, 2022). "KRAS mutation status was not significantly different according to the stage of the tumor." (PMID 36139531, 2022). "Consequently, different clones can present resistance by impeding the binding of drugs to KRAS G12C mutated cells and other tumor cells acquire resistance through mutations that are not targetable by KRAS G12C inhibitors." (PMID 35406400, 2022). "The supposition that KRAS mutant tumor cells have constitutive and enhanced macropinocytosis drives an interesting question: could such enhanced macropinocytosis be distinctive enough to act as a “phenotypic target” for KRAS mutant cancer, where targeted therapeutics are urgently needed?" (PMID 35154489, 2022). "In addition, B-Raf, as a key mediator of KRAS, was reported to drive tumor immune suppression." (PMID 36713514, 2022). "In vivo, KRAS siRNAGAT containing suppression of endogenous RNA (pSUPER) vector plus gemcitabine resulted in a prolonged survival rate of 64 days and dramatically reduced the mean tumor volume compared with single agents (52 days for gemcitabine, 45 days for KRAS siRNAGAT containing pSUPER vector)." (PMID 35652096, 2022). "We also show that increased expression levels of KSR1 decrease the responsiveness to the KRASG12C inhibitor sotorasib in human cancer cell lines, thus suggesting that increased levels of expression of KSR may make tumour cells less dependent on KRAS oncogenic signalling." (PMID 35313064, 2022). "Also, the tumor phospho‐Akt1/2/3 levels are not significantly different between different KRAS mutation status (one‐way ANOVA, P > 0.05)." (PMID 34919787, 2022). "Previous studies have confirmed that KRAS-driven cancer cells altered the content and structure of the tumor microenvironment, hence altering nutrient metabolism and oxygen availability in solid tumors, modifying the tumor microenvironment and limiting the proliferation and activity of T cells." (PMID 36172359, 2022). "Similarly to lung, the overall impact of Myc hypomorphism was a profound block in the transition of almost all indolent PanIN pre-tumour lesions to invasive cancer, temporally locating the Myc-dependent bottleneck post initial KRas activation but before the invasive expansion of early cancer." (PMID 36351945, 2022). "Besides tumor growth, KRAS could play a role in interactions between tumor cells and the microenvironment, which could affect therapeutic response." (PMID 35267628, 2022). "Notably, targeting of Rac1 by depletion of specific Rac-guanine nucleotide exchange factors (Rac-GEFs) fails to hinder the tumor growth in the presence of KRAS mutations, limiting its clinical use for advanced tumors." (PMID 35158939, 2022). "The results indicated that cancer could lead to the abnormal expression of KRAS in tumor tissues." (PMID 36330448, 2022). "Translational studies have suggested that KRASMUT patients might respond well to ICB due to a larger proportion of smokers and a higher immunologically active tumor environment as a consequence of constitutive activation of KRAS and downstream signaling pathways." (PMID 35565194, 2022). "In our study, the KRAS G12C mutation was associated with a MET mutation in four cases, indicating that there might be a need for adaptive treatment regimens according to the specific mutational profile of the tumor." (PMID 35205778, 2022). "The presence of KRAS sequence variation, one of the most common surrogates of tumor biological factors, appeared to trigger a distinct pattern of intrahepatic tumor growth and dissemination, which may affect the beneficial outcome of simultaneous resection in this patient subgroup." (PMID 36121654, 2022).
tumor (continued). "DdPCR targeting KRAS Q61H in H460 xenografted mice and EGFR T790M mutation in H1975 xenografted mice, identified a variation of ctDNA detection at similar tumor size, suggesting that the amount of ctDNA released during tumor growth may be specific to each cell line." (PMID 35628154, 2022). "However, clubbing PGG with other inhibitors may show synergistic or additive blockage of KRAS-driven tumor progression." (PMID 35928273, 2022). "Collectively, these data suggest that multiple tumor clones with distinct mitogenic drivers (either RET or KRAS) may co-exist at baseline, each shedding into circulation at different rates, ultimately leading to either short duration of at-best mixed response or primary resistance." (PMID 35304457, 2022). "Still, the existing data suggest that KRAS mutations in cancer cells can alter the behavior of fibroblasts, which in turn affect both the cancer cells and the microenvironment through extracellular matrix (ECM) changes and growth factor signaling, contributing to tumor progression." (PMID 36010567, 2022). "T3/N+ tumours may be already too invasive for KRAS-positivity to distinguish worse prognosis." (PMID 35194118, 2022). "SigG12D-LODERs is a polymeric matrix containing siRNAs that target the mutated KRAS oncogene, specifically KRASG12D, with high specificity and proven antitumor activity that consists in inhibiting KRAS translation with potential blocking effects of tumor growth." (PMID 36012138, 2022). "Some studies indicate that an initial mutation in KRAS leads to the formation of non-dysplastic polyps, which could represent an evolutionary dead end for neoplasias." (PMID 35416770, 2022). "KRAS mutation is reported to activate PI3K/Akt signaling; it is thus interesting to determine whether the PI3K/Akt pathway is similarly perturbed in primary tumor of CRC." (PMID 34919787, 2022). "This suggests that excessive tumor-generated HB-EGF might prevent PEPDG278D from binding to EGFR, and also suggests that EGFR signaling remains important to the tumors carrying activating mutations of KRAS, BRAF and/or PIK3CA." (PMID 35650607, 2022). "KRAS mutation was not related with pathologic characteristics of the tumor." (PMID 36139531, 2022). "KRAS G12C inhibitors could afford direct quantification of drug-bound KRAS G12C in tumor biopsies." (PMID 35267628, 2022). "Moreover, activation of KRAS was also reported to be associated with increased numbers of γδTCR+ inflammatory cells, which are a non-MHC-restricted lymphocyte subset closely associated with innate immunity and implicated in accelerated tumor formation." (PMID 35965494, 2022). "KRAS multi-site mutation was related to the presence or absence of mucus components and tumor size." (PMID 35837115, 2022). "In addition to being one of the first models to include KRAS mutation status as a surrogate of tumor biology, the GAME score differentiates itself from the previous models by incorporating the tumor burden score (TBS), a redefined CEA level (20 ng/mL) and extrahepatic disease." (PMID 35804994, 2022). "Moreover, cytoplasmic expression of KRAS was associated with resistance of pancreatic acinar cells to tumor-promoting KRAS mutations: KRAS mutants were expressed, but not properly located for exerting their function." (PMID 36238685, 2022). "Similarly, our study found that both in the PPE and the surrounding non-PPE tissues, the most common KRAS mutations were G12V and G12D, and G12D showed a significant higher frequency in the neoplasia samples." (PMID 35796805, 2022).
tumor (continued). "PDX CRC models maintain important gene mutations such as KRAS, BRAF (v-Raf murine sarcoma viral oncogene homolog B), PIK3CA (Phosphatidylinositol-4, 5-bisphosphate 3-kinase), gene expression, copy number changes, and microsatellite instability of the primary tumor." (PMID 35538576, 2022). "So, in addition to the KRAS mutational status, some authors propose to take into consideration not only the expression of PD-L1 but also other biological parameters such as the density of CD8 positive lymphocytes infiltrating the tumor cells when assessing the response to ICIs." (PMID 35406400, 2022). "Due to the rarity of KRAS mutation in RCC and its high incidence in PRNRP, KRAS mutation has become one of the most representative molecular markers that distinguish PRNRP from other PRCC subtypes, and it is likely to be a key driving factor in the tumorigenesis of this type of tumor." (PMID 36002896, 2022). "In one case (P004), a KRAS mutation was present in the plasma while we could not confirm it in the tumor." (PMID 35448266, 2022). "However, the presence of more than one KRAS mutation subtype within the same tumour has almost never been reported even in resection specimens, demonstrating that tumour heterogeneity is not a relevant consideration with respect to KRAS mutation subtype." (PMID 36231137, 2022). "The discrepancy between preclinical laboratory experiments and observations made in the clinic could be explained by the fact that some KRAS wt tumours can still activate the RAS pathway due to events other than RAS oncogene mutations, such as BRAF or EGFR mutation." (PMID 36163168, 2022). "Aurora kinases may interact with driver mutations of tumor cells, however, in vitro assays showed that reduction of cell invasiveness by pan-aurora kinase inhibition is independent of KRAS mutation status." (PMID 35332150, 2022). "Furthermore, intravenously injected iRGD exosomes containing KRAS siRNA could reach targeted lung tumour tissues in vivo, resulting in the notable inhibition of tumour growth in mouse models." (PMID 36290387, 2022). "Furthermore, sumoylation boosts tumor growth by maintaining KRAS (G12V) expression." (PMID 35922812, 2022). "First, we used unsupervised clustering methods to classify 375 tumour samples from The Cancer Genome Atlas (TCGA) database into three molecular subgroups (Cluster A, Cluster B, and Cluster C) based on the three characteristic pathways of GFRs: KRAS, AKT, and MTOR." (PMID 36387125, 2022). "Loss of the tumor suppressor PTEN hyperactivates phosphoinositide-3-kinase (PI3K)–AKT signaling and metabolic processes such as glucose metabolism, de novo lipid synthesis, and redox balance and cooperates with mutant KRAS-driven events in multiple PDAC models." (PMID 36151074, 2022). "Other recent studies in PDA have also illustrated how small subpopulations of cancer cells that survive inhibition of mutant KRAS signaling or are capable of anchorage-independent growth demonstrate enhanced utilization of mitochondrial oxidative phosphorylation relative to bulk tumor cells." (PMID 36411320, 2022). "Awaji found that KRAS mutation could promote the secretion of paracrine factors such as IL4, IL10, and IL13 in tumor cells and simultaneously activate CXCR2 signaling in CAFs, resulting in the formation of a secreted CAF phenotype by activating NF-κB signaling and promoting tumor progression." (PMID 36076911, 2022). "Molecular-targeted therapies were received by four of nine (44%) patients with KRAS wildtype mPDAC, which included afatinib (four patients) and post-afatinib administration of erlotinib (one patient), and were administered to patients based on an oncogenic fusion detected in their tumor." (PMID 36209277, 2022).
tumor (continued). "Therefore, advanced combination treatments including, e.g. CD40 agonists, TGFβ blockade, or therapeutics targeting KRAS signaling, the myeloid compartment, or tumor stroma may improve efficacy of virotherapy plus checkpoint blockade in PDAC." (PMID 36726983, 2022). "KRAS could affect tumor development through tumor immune cell infiltration." (PMID 35563733, 2022). "During tumor progression or recurrence, notably in patients treated with different anti-EGFR or anti-ALK TKIs, it is now well-admitted that a LB can be performed systematically to look for different druggable genomic alterations and this can include the detection of a KRAS G12C mutation." (PMID 35406400, 2022). "In this study, we concluded that high-grade tumor budding was strongly associated with unfavorable clinicopathological features, like a perineural invasion, venous invasion, and distant metastases, and special molecular biomarkers which are MSS status and KRAS mutations." (PMID 35096426, 2022). "Importantly, R273 mutants were associated with significantly shorter disease-specific overall survival than R175 mutants, regardless of patient age, tumor location or presence of KRAS mutations." (PMID 35589715, 2022). "In addition to the vertical signaling cascades involved in resistance, parallel pathways can bypass KRAS G12C inhibition through a variety of mechanisms, including tumour microenvironment alterations, alterations in cell cycle regulators, and phenotypic transformation." (PMID 36284306, 2022). "Therefore, activated KRAS is essential to tumor maintenance, as its removal results in apoptosis." (PMID 35883626, 2022). "With the observation that a variety of drug delivery systems could be internalized by KRAS mutant cancer cells through macropinocytosis, exploiting macropinocytosis for intracellular delivery of therapeutics into KRAS mutant tumor cells is emerging as a new drug delivery expedition." (PMID 35154489, 2022). "The genomic profile of the tumor was atypical as no KRAS mutation was detected." (PMID 34504655, 2021). "Even though studies have already proven that recombinant human TRAIL enhances the tumor sensitivity to chemotherapy/targeted therapy/radiotherapy in various cancer types, this may not apply to KRAS-mutated cancers." (PMID 33791337, 2021). "Additionally, in their in vivo studies, they have shown that mitochondrial inhibitors could decrease the KRAS-driven tumor growth." (PMID 34781949, 2021). "GSEA showed several tumor hallmarks were enriched in the high-risk group, such as interferon γ response, HEME metabolism, allograft rejection, interferon α response, complement, myogenesis, inflammatory response, KRAS signaling up, TNFα signaling via NF-κB and so on." (PMID 34869365, 2021). "Though not statistically different, the frequency of KRAS mutation seems to increase with the increasing G/T ratio, suggesting a relationship between KRAS mutation and tumor progression, resulting in a higher frequency in more progressed lung nodules presenting with GGOs." (PMID 34589430, 2021). "Researchers demonstrated that KRAS mutations, common in CMS3 CRC subtype, promote an immunosuppressive TME, inducing the conversion of CD4+ cells to Tregs [26, 27•] and, by upregulation of CXCL3 expression, the main ligand of CXCR2 on MDSCs surface, support their migration inside tumor core." (PMID 34110510, 2021). "We investigated survival among the following groups of patients: those with no KRAS mutations (wild type) versus those with mutated tumours, those with KRAS wild type versus KRAS G12C versus KRAS non-G12C mutated tumours and among patients with different KRAS mutation subtypes." (PMID 34503114, 2021). "Similar to sotorasib, adagrasib is a KRAS G12C inhibitor that has demonstrated a great activity on tumor regression in cell lines and patient-derived xenograft models, as well as in vivo, showing tumor regression in 65% of KRAS G12C mutant preclinical models including different tumor histotypes." (PMID 35004317, 2021).
tumor (continued). "However, while mutation of KRAS is a rare event in RCC, wild type KRAS may play a role in RCC cell proliferation and tumor growth." (PMID 34384473, 2021). "Further studies showed that SNORD50A/B could directly bind to and inhibit the activity of KRAS oncoproteins, indicating that it may exert tumor suppressor function in tumorigenesis and tumor progression by suppressing the activity of the KRAS/RAF/MEK/ERK pathway." (PMID 33742136, 2021). "While two patients (patients 2 and 3) lacked molecular intra-patient heterogeneity before immunotherapy, harboring only a KRAS mutation or no evident driver mutation, the primary tumor of patient 1 showed a heterogeneous molecular profile with several different clones and different driver mutations." (PMID 34072863, 2021). "This correlation was enhanced in patients with conserved miR-let-7a-binding sequence in KRAS-coding mRNA, suggesting that patients with high tumor expression of miR-let-7a may benefit from an anti-EGFR therapy irrespective of KRAS mutational status." (PMID 34208056, 2021). "In addition, pulse MEK treatment combined with CTLA-4 blockade can prolong the survival time of KRAS-mutant tumour in mice, which may be related to T cell activation and increased CTLA-4 expression due to MEK pulse therapy." (PMID 34012925, 2021). "In this study, the combination of a MEK1/2 inhibitor (AZD6244) and a PI3K inhibitor (BEZ235) in tumor-bearing mice showed initial reduction and subsequent inhibition of tumor growth, suggesting that this combination therapy might enhance anti-tumor activity in KRAS mutant cells." (PMID 34064352, 2021). "In addition, combination therapy in KRAS-driven lung tumors resulted in prominent induction of cellular senescence and infiltration of tumors with activated NK cells, which drove tumor cell clearance, and markedly increased survival in dual-treatment mice compared to single agent treated mice." (PMID 33821796, 2021). "Moreover, the expression of KRAS and PGD was positively related to tumor mutation burden, indicating that KRAS and PGD could serve as novel biomarkers for predicting immunotherapy response rate." (PMID 34434214, 2021). "Interestingly, previous study demonstrated that tumor cells with autophagy-dependent ferroptosis could release KRAS protein, which was further packaged into exosomes to promote tumor-associated macrophage (TAM) polarization to exert immunosuppressive effects." (PMID 33738257, 2021). "Furthermore, genetic deletion of SLC7A11 or pharmacological inhibition with sulfasalazine (SAS) selectively killed KRAS mutant cancer cells in vitro and inhibited tumor growth in vivo, suggesting the functionality and specificity of SLC7A11 as a therapeutic target." (PMID 34502181, 2021). "While the MC38 orthotopic tumor model serves as a syngeneic murine model generated from wt-KRAS, MSI-H, and p-53 mutant MC38 cell line, we demonstrated as a proof-of-concept, the combination treatment could be effective in studying the mechanisms of immune modulation in response to CB." (PMID 34381456, 2021). "The findings of the present MPLC study confirms that some cases with EGFR- or KRAS- mutated tumours are strongly related to non-intrinsic factors and suggests that the other most mutations may occur by chance." (PMID 33707471, 2021).